RNU6-695P (RNA, U6 small nuclear 695, pseudogene)
Gene: Small nuclear RNA gene on chromosome 1 (90,253,456 to 90,253,559, reverse strand). Ensembl gene ENSG00000212459.
Homologues: Orthologues: chimpanzee U6 (95% identical), macaque U6 (87% identical), dog U6 (79% identical), rabbit U6 (76% identical), zebrafish U6 (71% identical). Paralogues in human: RNU6-774P (83% identical), RNU6-144P (81% identical), RNU6-97P (81% identical), RNU6-10P (80% identical), RNU6-11P (80% identical), RNU6-154P (80% identical), RNU6-15P (80% identical), RNU6-235P (80% identical), RNU6-263P (80% identical), RNU6-312P (80% identical), RNU6-333P (80% identical), RNU6-379P (80% identical), and 1284 more.